RN7SL833P (RNA, 7SL, cytoplasmic 833, pseudogene)
Gene: Miscellaneous RNA gene on chromosome 19 (11,516,047 to 11,516,330, reverse strand). Ensembl gene ENSG00000244080.
Homologues: Orthologues: chimpanzee Metazoa_SRP (100% identical), macaque Metazoa_SRP (87% identical). Paralogues in human: RN7SL2 (83% identical), RN7SL1 (82% identical), RN7SL122P (81% identical), RN7SL187P (80% identical), RN7SL45P (80% identical), RN7SL732P (80% identical), RN7SL3 (80% identical), RN7SL444P (80% identical), RN7SL559P (80% identical), RN7SL709P (80% identical), RN7SL865P (80% identical), RN7SL127P (80% identical), and 704 more.